ENSG00000276642
Synonyms: LOC124900455
Gene: Small nuclear RNA gene on chromosome 1 (220,825,776 to 220,825,893, forward strand). Ensembl gene ENSG00000276642.
Gene Ontology:
Molecular function: pre-mRNA 5'-splice site binding; U4atac snRNA binding
Biological process: mRNA 5'-splice site recognition; spliceosomal tri-snRNP complex assembly
Cellular component: U6atac snRNP
Homologues: Paralogues in human: RNU6ATAC (86% identical), RNU6ATAC21P (82% identical), RNU6ATAC6P (81% identical), RNU6ATAC8P (80% identical), RNU6ATAC7P (79% identical), RNU6ATAC27P (78% identical), RNU6ATAC41P (78% identical), RNU6ATAC19P (63% identical), RNU6ATAC39P (58% identical), RNU6ATAC22P (48% identical).